CRP (C-reactive protein)
Diseases named in the same sentence as CRP in open-access papers (continued):
Sharing a sentence is not in itself a finding about the gene and the disease.
Obesity (continued). "While elevated CRP is suggestive of inflammation or infection in the appropriate clinical context, it can also occur with obesity, renal dysfunction, cardiovascular disease, and many other chronic diseases." (PMID 30538987, 2018). "Sleep loss, for instance, is known to induce proinflammatory markers CRP, Interleukin-6 (IL-6) and TNF that are associated with depression and obesity." (PMID 30524737, 2018). "Obesity and T2DM are also associated with increased inflammation, with elevations of serum C reactive protein (CRP), plasma fibrinogen, and other acute-phase proteins." (PMID 29747432, 2018). "The relationship between CRP and NT-proBNP, a biomarker with reduced sensitivity for the diagnosis of HF in the setting of obesity, was only significant after adjusting for other variables, such as BMI." (PMID 30114262, 2018). "CRP is therefore related to cardiovascular risks, dyslipidemias, obesity, and atherosclerosis, in which lipoproteins are also important." (PMID 29189992, 2018). "In our case, several biological experiments, including Mendelian randomization studies, strongly implicate the precedence of obesity over chronic inflammation reflected in rising CRP levels." (PMID 30123515, 2018). "Several clinical studies have shown a correlation between increased plasma levels of both CRP and leptin in subjects with obesity, CVD, and diabetes." (PMID 29910808, 2018). "Pregravid obesity is characterized by insulin and leptin resistance, high levels of circulating inflammatory markers IL-6 and CRP, in addition to chemokine IL-8 (p < 0.01)." (PMID 30131724, 2018). "Some authors demonstrated that obesity is associated with an inflammatory process, characterized by increased circulating levels of inflammatory cytokines such as TNF-α, IL-6, and C-reactive protein (CRP)." (PMID 29780825, 2018). "Subjects with obesity havea 5.6-fold higher chance to present with increased CRP than subjects withlean/normal BMI." (PMID 29513800, 2018). "Comparably higher systemic C-reactive protein (CRP) with regional obesity of the abdomen is another aspect of cardio-metabolic disease that contrives to increase CVD in SAs when compared with CAUCs." (PMID 30918627, 2018). "As reported in earlier studies, this appears to be related to obesity as indicated by a positive correlation between BMI and leptin and CRP." (PMID 29910808, 2018). "Our study found that when obesity and other controls were added as covariates, the odds of having a CRP level >1 mg/dL in the sleep apnea group decreased substantially, to nonstatistical significance (OR=2.46 compared to OR=1.33)." (PMID 30402295, 2018). "In established obesity, omentectomy eliminates the omental production of inhibitors of the leptin and insulin effects, particularly CRP and IL-6." (PMID 29367725, 2018). "Sex-stratified analyses: in men, ever-smoking, obesity and high baseline CRP predicted progression defined as ≥2 mSASSS units over 5 years." (PMID 30075808, 2018). "Low grade inflammation plays a role in the development of obesity and metabolic disorders and in a recent report, elevated serum levels of CRP and TNF-α in 300,000 μkd DEHP in utero exposed offspring were detected." (PMID 30519216, 2018). "Systemic inflammation is up-regulated with obesity with the acute inflammatory phase marker, C-reactive protein (CRP), higher in obese people." (PMID 30021590, 2018). "When we examined participant characteristics by obesity status, those subjects at greater weight had significantly higher age, BMI, CRP, and RDW, and lower ASM." (PMID 30065297, 2018). "In this context, the potential role of CRP in modulating the action of leptin in obesity is relevant." (PMID 29910808, 2018). "Accordingly, BMI at baseline – available for a subgroup of our study population – showed a strong direct relationship with CRP levels (OR of CRP ≥ 2 mg/L was 5.26; 95% CI: 3.94–7.03, for obesity vs. normal weigh)." (PMID 30150729, 2018).
Obesity (continued). "As noted in the obesity section, increased BMI or obesity is related to greater systemic inflammation (e.g., CRP, IL-6, and TNF-α levels)." (PMID 30538987, 2018). "Omentum removal reversed immediately the increased plasma levels of CRP and IL-6 and gradually food intake, weight gain, and features of MS in diet-induced-obesity." (PMID 29367725, 2018). "Specifically, C-reactive protein (CRP) has emerged not only as a powerful predictor of CVD but also as a possible mechanism in the relationship between obesity and CVD." (PMID 30439985, 2018). "We investigated circulating tryptophan, kynurenine and its metabolites, neopterin, B-vitamins, CRP, and HbA1c in individuals with obesity before and after bariatric surgery." (PMID 29401505, 2018). "Differences in the number ofpatients with increased CRP are observed, as well as a tendency for higher CRPvalues in subjects with obesity over lean/normal BMI." (PMID 29513800, 2018). "The data of confounding factors including sex, age, HBP, hyperlipidemia, DM, smoking, alcohol, obesity, white blood cell, and hypersensitive C-reactive protein in ICH patients and healthy controls were extracted from the included studies." (PMID 30619067, 2018). "Omentum drives obesity progression through leptin resistance mediated by C-reactive protein, Interleucin (IL)-6 and high lipolysis activity." (PMID 29367725, 2018). "Results showed improvements in obesity-related inflammatory profiles after following plant-based diets: CRP (−0.55 mg/L), IL-6 (−0.25 ng/L), and sICAM-1 (−25.07 ng/mL)." (PMID 30544955, 2018). "In our study, there were significant differences in baseline characteristics between the first-generation and second-generation immigrants (HbA1c, obesity, serum CRP and socioeconomic status)." (PMID 29891972, 2018). "The metabolic profile of the insulin-sensitive men with obesity in the present study was consistent with previous reports, including lower glycaemia, fasting insulin, and CRP." (PMID 28293196, 2017). "In fact, the development of insulin resistance and type II diabetes, even independent from obesity, can be predicted by an increase in inflammatory markers like interleukin 6 (IL-6) and C-reactive protein (CRP)." (PMID 28704429, 2017). "These relationships were present before, and after, adjusting for age, sex, obesity/overweight status, C-reactive protein levels, and residential proximity to the study area’s major roadway." (PMID 28424616, 2017). "Overweight/obesity, which is considered a chronic inflammatory condition, increases the levels of plasma C-reactive protein and certain inflammatory cytokines." (PMID 29191156, 2017). "We observed that patients with fibromyalgia and overweight/obesity had increased CRP levels and that this group was the only one with a correlation, albeit weak, between CRP and FIQ scores." (PMID 28226002, 2017). "In a number of studies, serum CRP levels have been found to correlate with the degree of low-grade vascular inflammation in people with obesity and MS, which links hyperuricemia and vascular injury." (PMID 29321950, 2017). "In a comparison between the group of fibromyalgia and overweight/obesity versus that of fibromyalgia with normal weight, the CRP levels were higher in the former (0.42 ± 0.41 mg/dL versus 0.19 ± 0.18 mg/dL, respectively; p < 0.05)." (PMID 28226002, 2017). "One of the main effects of IL-6 is the induction of hepatic CRP and FIB production, playing a key role in the inflammatory processes associated with obesity." (PMID 28061787, 2017). "All HFD rats developed obesity, hyperglycemia, hypertriglyceridemia, increased levels of CRP and UA (when compared to the control group), and oxidative stress with high levels of malondialdehyde and low levels of reduced glutathione." (PMID 29321950, 2017).
Obesity (continued). "In the group of patients with fibromyalgia and overweight/obesity, the CRP levels correlated directly with values of WC, BMI, and fat mass, demonstrating an inflammatory component associated with overweight and obesity." (PMID 28226002, 2017). "Insulin resistance and obesity are characterized by a low-grade but chronic inflammatory state, with elevated circulating levels of CRP, TNF-α, IL-6 and leptin and reduced ACDC concentrations associated with increased cardiometabolic risk." (PMID 29020958, 2017). "Obesity is a chronic inflammatory disorder in which leptin, adiponectin and CRP play an important role." (PMID 27598978, 2017). "Age, race, education,income, asthma, COPD, C-reactive protein, obesity, smoking,alcohol drinking, physical inactivity, and menopausal status." (PMID 28086228, 2017). "In conclusion, the present study demonstrated a clear association between obesity and COC use on alterations in metabolic parameters, notably HDL-c and CRP, which are known to contribute to the development of CVD." (PMID 29033897, 2017). "Many subjects in this study tended toward obesity, and showed typical symptoms of adiposity, including abnormally high levels of the inflammation marker CRP." (PMID 29058588, 2017). "In this way, our results regarding levels of MDA are in-line with previous findings and the levels of CRP corroborate studies relating to the presence of obesity with chronic low-grade inflammation." (PMID 28555008, 2017). "In a study on the relationship between obesity and CRP in the children, the results showed that the obese children had significantly increased CRP." (PMID 28115972, 2017). "In line with previous evidence from other authors, an association between obesity and higher serum concentrations of leptin, MDA, CRP and glucose was corroborated in our study." (PMID 28555008, 2017). "The positive correlation between increased level of C-reactive protein (CRP) and obesity confirm the fact that this disease is also a chronic inflammatory state, which can potentially lead to cardiovascular diseases." (PMID 28814950, 2017). "Previous studies have demonstrated that PS and obesity share common inflammatory mediators such as CRP and IL-6." (PMID 28947858, 2017). "Obesity is associated with an elevated secretion of proinflammatory cytokines, including IL-6, TNF-alpha, and C-reactive protein, and obesity is posited to be a state of chronic inflammation." (PMID 28428966, 2017). "CRP has been extensively studied in OSA and is often found elevated in OSA patients, especially in association with obesity, dyslipidemia, diabetes, and cardiovascular diseases." (PMID 28831208, 2017). "The levels of inflammatory cytokines, like interleukin-6 (IL-6) and tumor necrosis factor-alpha (TNF-α), as well as C-reactive protein (CRP) are elevated in obesity and insulin-resistant states." (PMID 28836404, 2017). "The role of diet or exercises in reducing serum CRP and thereby modulating obesity was also supported by large body of evidences." (PMID 28115972, 2017). "Obesity and COC use were associated with alterations in lipid and inflammatory cardiometabolic parameters, particularly increased CRP levels and decreased HDL-c, which are considered markers of cardiovascular disease (CVD) risk." (PMID 29033897, 2017). "Using NHANES data, the association of flavonoid consumption and multiple markers for obesity including: body mass index (BMI), waist circumference and C-reactive protein were explored." (PMID 28504712, 2017). "Serum concentrations of hsCRP were significantly higher in obese than in non-obese PCOS patients at baseline, suggesting a relationship between elevated hs-CRP levels and obesity." (PMID 28042411, 2017). "Other interfering situations on GA levels already described are age, obesity and inflammatory conditions (observed by the increase of C-reactive protein), smoking, and hypertriglyceridemia." (PMID 28699985, 2017).
Obesity (continued). "Participants in the obesity group had a higher HOMA-IR value, BMI level, systolic blood pressure (SBP), glucose, alanine aminotransferase (ALT), uric acid (UA), and C-reactive protein (CRP) compared with the non-obesity group." (PMID 29108358, 2017). "It has also been proposed that IL-6 released from adipocytes stimulates hepatic synthesis of C-reactive protein (CRP) in obesity." (PMID 26942201, 2016). "Metabolic inflammation increases the level of CRP which strongly correlates with the degree of obesity." (PMID 28097156, 2016). "Conversely, in an interesting Japanese study, increased visceral fat mass, as measured by tomography, was an independent predictor for the elevation of CRP levels in individuals with mild obesity or reduced glucose tolerance." (PMID 26862350, 2016). "BMI, blood pressure, fasting glucose, triglyceride, HOMA-IR, and CRP were significantly higher in the obesity group than in the control group (all P values lower than 0.001)." (PMID 27787389, 2016). "When the entire sample was evaluated together, α-MSH levels were negatively correlated with various parameters of obesity, including weight z-score, BMI, BMI z-score, BMI percentile, as well as insulin and CRP levels." (PMID 26758700, 2016). "Recently, we have reported that chronic inflammation, assessed by repeated measures of CRP, was associated with increased VTE risk and partly explained the association between obesity and VTE risk, particularly in women." (PMID 27997594, 2016). "Sex‐specific associations of serum leptin and C‐reactive protein (CRP) with cancer death in the NHANES III, stratified by obesity status." (PMID 26632325, 2016). "In fact, increased circulating levels of pro-inflammatory mediators such as C-reactive protein (CRP), tumor necrosis factor α (TNFα), monocyte chemoattractant protein-1 (MCP-1) and interleukin-6 (IL-6) have been observed in obesity-associated IR." (PMID 27111539, 2016). "Obesity also induces “smoldering” inflammation causing a permanently elevated level of cytokines (TNF alpha, IL-6, CRP) which promote tumurigenesis." (PMID 26951106, 2016). "Because obesity is associated with low-grade inflammation, ESR and CRP levels can result in elevated independently of disease activity." (PMID 27964760, 2016). "Among inflammatory biomarkers, the role of classic inflammatory mediators including tumor necrosis factor α (TNF-α) and C-reactive protein (CRP) have been extensively investigated in obesity." (PMID 26909479, 2016). "Our findings correlate with those observations as we found advanced age, DM, obesity (BMI >25 kg/m2), CRP and CKD were independent predictors of elevated GDF-15 in patients with CAD who needs PCI." (PMID 27056183, 2016). "CRP is strongly linked to cardiovascular disease as well as to components of metabolic syndrome, including insulin resistance, although a recent study suggested that obesity is the major determinant of the CRP/insulin resistance relationship." (PMID 27249024, 2016). "It has been confirmed that concentrations of pro-inflammatory cytokines such as TNF-α, IL-6 and CRP are elevated in obese subjects and elevated TNF-α, IL-6 are associated with obesity related insulin resistance." (PMID 27409634, 2016). "Higher circulating levels of TGF-β are related to obesity with impaired insulin sensitivity, cardiovascular diseases among individuals with higher C-reactive protein (CRP) levels, type II diabetes, and a higher age." (PMID 27375767, 2016). "HIF3A expression was significantly higher in SAT compared to VAT and correlated with obesity and parameters of AT dysfunction (including CRP and leucocytes count)." (PMID 27346320, 2016). "They suggested that low SEP is associated with an increased susceptibility to inflammation, and that inflammatory challenges (high levels of CRP, obesity) are most adverse in individuals with low SEP." (PMID 26751953, 2016).
Obesity (continued). "A raised systemic inflammatory profile is a characteristic feature of obesity, evidenced by the raised levels of c-reactive protein (CRP) and IL-6." (PMID 25705177, 2015). "FL was found in 480 enrolled patients, and significant differences were observed between the non-FL group and FL group, in gender, etiology, BMI, the rate of obesity and the concentration of serum C-reactive protein (CRP) within 24 h after the onset of AP." (PMID 26571385, 2015). "Obesity-induced chronic microinflammation is characterized by increased production of proinflammatory cytokines such as IL6 that in turn induces CRP production in the liver and secretion into the blood." (PMID 25922641, 2015). "We then repeated our analysis stratified by prepregnancy BMI as previous studies have shown differences in the impact of an exercise intervention on CRP according to obesity." (PMID 26104503, 2015). "Among females, the adjusted geometric mean for the hs-CRP level in the obesity only group (0.20 mg/dL) was also significantly higher than that in the normal group." (PMID 26177029, 2015). "Obesity, which is an established risk factor for CVD and T2DM, has been associated with elevated levels of CRP." (PMID 25671415, 2015). "Obesity is associated with chronic inflammatory status in CRC, high circulating levels of C-reactive protein have been shown to be associated with poor prognosis in CRC." (PMID 26082438, 2015). "In the female population we observed a high percentage of individuals with obesity grade 3 (7.9%) and hs-CRP levels above 3 mg/L (58.2%)." (PMID 26474291, 2015). "It is also recognized that plasma leptin and CRP levels are upregulated in obesity and proinflammatory states and closely related." (PMID 25929254, 2015). "A meta-analysis of 26 studies matching carefully for BMI revealed that CRP is elevated in PCOS independently of obesity." (PMID 26124830, 2015). "As CRP is the prevailing index of inflammation, the CRP concentration elevations seemingly validate a link between obesity and endometrial cancer." (PMID 26107255, 2015). "In the sarcopenic obesity group, the mean hs-CRP level was the highest compared with those in the other groups." (PMID 26177029, 2015). "In our results, the relative times spent in SB and LIPA were both detrimentally associated with obesity markers, HDL, CRP and blood pressure, while MVPA showed a health enhancing relationship." (PMID 26461112, 2015). "Here, as well as in our previous study, we showed that high liver fat is associated with several preclinical metabolic aberrations in obesity, including increased glucose, insulin, lipid, and CRP levels." (PMID 25866590, 2015). "The BMI value and the rate of obesity in patients with FL were also higher, as well as the serum CRP level." (PMID 26571385, 2015). "In the baseline evaluation, 29.2% had MetS (hypertriglyceridemia 66%, hypertension 44% and obesity 37%); patients with MetS had higher C reactive protein (CRP) levels [34.1 ± 28.6 vs. 12.2 ± 11.2 mg/dL, P = 0.033]." (PMID 26131838, 2015). "Plasma CCL-5 (also called regulated on activation, normal T cell expressed and secreted or RANTES), and CRP are typical markers of systemic inflammation while the increased triglyceride levels are clinical indicator of obesity." (PMID 26312071, 2015). "In the male population only 3.2% had grade 3 obesity and most participants had hs-CRP levels ≤3 mg/L (68.9%)." (PMID 26474291, 2015). "Left atrium enlargement and systemic inflammation are both probable effect mediators between obesity and the development of AF and low levels of CRP has been suggested to play a role in the protective profile of MHO individuals." (PMID 25978738, 2015). "Across all studies, l-ascorbic acid was associated with smoking status, alcohol intake, physical activity, and socioeconomic position alongside obesity, insulin, C-reactive protein, IL-6, and urate (where available)." (PMID 25527764, 2015).